MITF (melanocyte inducing transcription factor)
Diseases named in the same sentence as MITF in open-access papers (continued):
Sharing a sentence is not in itself a finding about the gene and the disease.
melanoma (continued). "Likewise, dysregulation of MITF protein results in the development of melanoma progression and drug resistance." (PMID 38275910, 2024). "Moreover, contrary to previous assumptions, amelanotic melanoma cells retain the ability to produce melanin, as demonstrated by the expression of tyrosinase and MITF." (PMID 39519055, 2024). "It is possible that MITF might directly regulate ferroptosis or other changes in cell metabolism in melanoma; however, future studies are required to assess the role of MITF in regulating sensitivity to ferroptotic cell death." (PMID 39277608, 2024). "Based on the correlation between MITF expression and its related function in melanoma, miR-211-5p may represent a surrogate marker for MITF." (PMID 39409187, 2024). "In addition, this redox program is correlated with MITF expression in human melanoma cell lines and patient-derived melanoma samples." (PMID 39277608, 2024). "Indeed, de-differentiation of melanoma cells towards NCSC states (which have low MITF activity) is one mechanism in which melanoma cells escape T-cell detection and respond to inflammation, such as TNFα." (PMID 39092608, 2024). "In addition to its role in melanin synthesis, MITF is also involved in the survival and differentiation of melanocytes, and MITF upregulation has been identified in melanoma." (PMID 38790649, 2024). "In addition, MITF regulates melanin production and cell survival pathways and plays a dual role in promoting melanoma progression while also inhibiting invasion." (PMID 39519055, 2024). "MITF gene is reported to be amplified in about 20% of melanoma, so targeting MITF could be a promising approach for treating melanoma." (PMID 38586368, 2024). "For instance, miR-148a and miR-101 show a significant impact on MITF expression in melanoma cells." (PMID 38553490, 2024). "Interestingly, tumor tissue samples showing a higher percentage of CD8+ cells and lower abundance of MITF+ melanoma cells were taken post-treatment (purple dots), suggesting that DC vaccination or ipilimumab has enhanced immunoreactivity against these cells." (PMID 39697983, 2024). "Observing increased IFNγ-induced PD-L1 expression in the dedifferentiated 624Mel cells is partly in line with previous studies where SOX10 knockdown, which reduces MITF expression in melanoma cells, led to increased IFNγ-induced PD-L1 expression in three out of four tested melanoma cell lines." (PMID 39736644, 2024). "Additionally, inhibition of the cAMP-dependent signaling pathway degrades MITF in α-MSH-stimulated melanoma cells." (PMID 39203053, 2024). "We hypothesize that the early exposure to MAPK inhibitors selects drug tolerant melanoma cells characterized by the block of proliferation due to the activation of MITF/miR-579-3p axis." (PMID 38472212, 2024). "Interestingly, MITF-independent regulation of melanization gene expression is observed in some melanoma cells." (PMID 39228400, 2024). "A critical regulator in the MAPK pathway that plays a key role in melanocyte differentiation and melanoma malignancy is the microphthalmia-related transcription factor (MITF), whose regulatory activities include genes integral to cell cycle progression, proliferation, and immune escape mechanisms." (PMID 39519202, 2024). "Notably, prior researches have demonstrated that MITF drives AC expression and that it is downregulated in invasive melanoma cells." (PMID 39136013, 2024). "The MITF serves as an oncogene and is expressed in approximately 80% of human melanomas." (PMID 39000342, 2024). "To further investigate what may facilitate this difference in PD-L1 expression, we compared the top and bottom quartiles of the melanoma cell lines, ranked by MITF expression." (PMID 39736644, 2024). "To further characterize the effect of MITF knockdown and IFNγ treatment on the differentiation status of 624Mel cells, we performed GSEA using established gene sets that specifically associate with differentiation stages in melanoma cells." (PMID 39736644, 2024).
melanoma (continued). "We used the MiniCoopR system to overexpress human MITF in melanoma-prone zebrafish." (PMID 39277608, 2024). "In addition to its role as key regulator of melanoma progression and invasion, MITF is one of the main determinants of melanoma heterogeneity and therapy resistance." (PMID 38275910, 2024). "However, to our knowledge, this is the first study to directly link MITF expression alone with the IFNγ response in melanoma cells." (PMID 39736644, 2024). "In order to investigate whether MITF controls ROS levels in vivo, we examined a zebrafish melanoma model." (PMID 39277608, 2024). "It has been shown that the MITF gene is amplified in certain melanoma and thus it may be related to adaptation to high ultraviolet environments at high altitudes." (PMID 38565986, 2024). "ZEB2 supports melanoma cell proliferation and differentiation by activating MITF expression." (PMID 38519642, 2024). "Indeed, our data suggest that oncogenic BRAF is able to control the levels of its natural inhibitor miR-579-3p through MITF regulation, thereby, preserving melanoma cells from the oncosuppressive functions of this microRNA." (PMID 38472212, 2024). "MITF coordinates many biological properties of melanocytes and might be used as a key molecular marker to distinguish between differentiated, proliferative (MITF+/high), or invasive (MITF−/low) melanoma phenotypic states." (PMID 38191367, 2024). "Interestingly, Western Blot analyses revealed that melanoma cells characterized by the highest levels of p-ERK (i.e. WM115) showed the lowest levels of MITF expression and vice versa." (PMID 38472212, 2024). "ARID2 mutations in melanoma may alter chromatin accessibility, potentially leading to abnormal transcription by MITF and consequently contributing to melanoma development and progression." (PMID 39727945, 2024). "MAFF mRNA has been implicated in melanogenesis by forming a heterodimer with NRF3 in response to stress, whereas the TFEB gene would cross-regulate with MITF in cellular clearance pathways and induce melanoma growth by participating in metabolic regulation and ERK1/2 activation." (PMID 39594467, 2024). "Therefore, this study sought to investigate the effects of T. himalayense NIBRFG0000505337 on the expression of tyrosinase, TRP-1, TRP-2, and MITF in α-MSH-treated B16F10 melanoma cells." (PMID 38480002, 2024). "This study investigates how MITF interacts with immune cells, and how it might influence treatments for diseases like melanoma." (PMID 38351314, 2024). "Another intriguing aspect of this study was that the authors opted to investigate the intermittent drug treatment with the chemotherapeutic agent dacarbazine, and they showed BRAFi-addicted melanoma cells were sensitized to this compound accompanied with MITF inhibition." (PMID 38485987, 2024). "SiRNA mediated MITF knockdown in 624Mel melanoma cells in combination with IFNγ (5 ng/mL) treatment significantly increased PD-L1 expression at both the RNA (one-way ANOVA, P < 0.01) and protein levels (one-way ANOVA, P < 0.001) compared to the expected increase caused by IFNγ treatment alone." (PMID 39736644, 2024). "Also MITF levels are reported to govern the balance between sensitivity and targeted therapy resistance in melanoma." (PMID 38472212, 2024). "Notably, CSE1L promotes melanin formation and melanoma progression by influencing the expression and phosphorylation of CREB (cAMP response element binding protein) and MITF (microphthalmia-associated transcription factor)." (PMID 39430746, 2024).
melanoma (continued). "To this aim, we exposed LOX IMVI sensitive melanoma cells to increasing concentrations of a BRAFi for two months and at each step of drug increase we collected total RNAs from samples to evaluate the levels of mir-579-3p, MITF, TYR, and AXL by qRT-PCR." (PMID 38472212, 2024). "For this reason, MITF biological functions must be tightly regulated in melanoma cells." (PMID 38472212, 2024). "It belongs to the microphthalmia family of evolutionarily conserved members in the vertebrates, also including TFEC, TFE3, and MITF (microphthalmia-associated transcription factor), whereby the latter one has recently been shown to play a key role in TPC2/Rab7a-driven effects in melanoma cells." (PMID 39682251, 2024). "Indeed, the antioxidant MITF target, PGC1α, has been demonstrated to augment the proliferation of a subset of melanoma cell lines, while concurrently suppressing the metastatic potential of these cells." (PMID 39277608, 2024). "Apart from the significance of the MITF/AXL ratio in the development of resistance to BRAFi, MITFlow/JARID1Bhigh and MITFhigh/PGC1αhigh (PPARG coactivator 1 alpha) ratios also have been linked to drug resistance in melanoma." (PMID 38672652, 2024). "MITF is known to affect our skin color and the development of melanoma." (PMID 38351314, 2024). "Along with the results observed in B16 mouse melanoma cells, the relative gene expression levels of MITF, TYR, TRP-1, and DCT, after exposure to IBMX treatment, were significantly upregulated to 1.65 ± 0.12, 1.73 ± 0.15, 1.53 ± 0.12, and 1.67 ± 0.13, respectively, compared to the control group." (PMID 39684912, 2024). "Additionally, NRF2 expression was noted in all cell types at a lower expression than that of MITF in melanoma cells." (PMID 38790661, 2024). "Moreover, acid ceramidase (AC) has been identified as a direct transcriptional target of MITF and a key enzyme in the invasive to proliferative phenotypic switch of melanoma cells." (PMID 39136013, 2024). "Fibronectin, secreted by melanoma cells themselves, is associated with enhanced migratory and proliferative properties in in vitro assays, as well as expression of EMT markers along with a downregulation of MITF in patient samples." (PMID 38419052, 2024). "Thus, in melanoma, MITF promotes proliferation, suppresses senescence, and is inversely correlated with immune infiltration." (PMID 39409187, 2024). "To do that, we induced dedifferentiation in 624Mel melanoma cells via siRNA mediated MITF knockdown and treated the cells with IFNγ and then performed bulk RNA sequencing on both differentiated (siCTRL) and dedifferentiated (siMITF) 624Mel cells, with or without IFNγ treatment." (PMID 39736644, 2024). "Interestingly, several identified genes and/or pathways, were common to those identified in signatures from several MRD melanoma models such as the neural crest stem cells, MITF targets, differentiation/pigmentation and invasion." (PMID 39223638, 2024). "Beyond its role in melanoma and melanocytes differentiation, MITF has been reported to be essential for the regulation of genes implicated in several biological processes such as survival, cell cycle control, invasion, autophagy, senescence bypass, and DNA damage repair and chromosome stability." (PMID 38275910, 2024). "Understanding the basis of melanoma biology, and especially the differences between high and low MITF melanomas, may not only help in the design of tailored prevention strategies but also lay the groundwork for future therapeutic directions." (PMID 39277608, 2024). "MITF and miR-211-5p show a high correlation in their expression in melanoma in TCGA dataset." (PMID 39409187, 2024). "However, MC extract administration decreased the expression of these tumor survival genes; this finding suggests that the MITF pathway is involved in the suppression of melanoma proliferation and invasion by the MC extract." (PMID 39684511, 2024).
melanoma (continued). "Previous MITF ChIP-seq analyses demonstrated that MITF directly and positively regulates genes involved in DNA replication, repair and mitosis, while repressing genes involved in melanoma invasion." (PMID 38519642, 2024). "Moreover, a low MITF/high Axl (a receptor tyrosine kinase) ratio was reported in a subpopulation of slowly proliferating melanoma cells endowed with invasive properties and drug resistance." (PMID 39199632, 2024). "Moreover, both extracts demonstrated potential for inhibiting melanin production and intracellular tyrosinase activity in human melanoma cells by decreasing the expression of the transcription factor MITF and the pigmentary genes TYR, TRP-1, and DCT." (PMID 38999635, 2024). "Accordingly, C/EBPβ, SMAD3 and MITF are directly related to melanoma dedifferentiation." (PMID 39136013, 2024). "MITF also plays a critical role in melanoma development and progression." (PMID 39562548, 2024). "Importantly, we also observed a significant correlation across 474 patient melanoma samples from TCGA, suggesting that the MITF-driven redox program is relevant in-patient biopsies despite the presence of non-malignant stromal and immune cell populations." (PMID 39277608, 2024). "Importantly, MITF is recognized as a major determinant of phenotypic identity in melanoma cells where it promotes differentiation by both positive regulation of melanocytic genes and by repressing expression of genes that induce dedifferentiation." (PMID 39736644, 2024). "Besides the identification and molecular characterization of the new MITF/miR-579-3p axis, we have also provided evidences about the biological effects of this interplay in melanoma." (PMID 38472212, 2024). "MITF−/low melanoma cells in CM correspond to melanoma-initiating cells (MIC)." (PMID 38191367, 2024). "Given that miR-579-3p and MITF are co-regulated in melanoma, we decided to investigate whether this transcription factor may be able to regulate ZFR/miR-579 gene." (PMID 38472212, 2024). "Furthermore, MITF−/low melanoma cells strongly expressed the Nerve Growth Factor Receptor (NGFR/CD271) identified as a marker of MICs and, partially, the epithelial-to-mesenchymal transition (EMT) marker ZEB1." (PMID 38191367, 2024). "MITF significantly and positively correlated with reduced glutathione levels in both datasets, suggesting that it potentially plays a functional role in regulating cellular glutathione levels in melanoma." (PMID 39277608, 2024). "Given that i) miR-579-3p is a negative regulator of BRAF-V600-MAPK signaling and ii) miR-579-3p expression is under the transcriptional control of MITF, we decided to measure MITF protein levels following MAPK signaling pathway inhibition in BRAF-mutant melanoma cells." (PMID 38472212, 2024). "In contrast, the MITF exerts an anti-proliferative effect by activating p21Cip1 in melanoma cells." (PMID 39000342, 2024). "Additionally, doxycycline enhances the expression of microphthalmia-associated transcription factor (MITF), a transcription factor involved in melanin synthesis and potentially linked to cell cycle regulation in melanoma." (PMID 39858295, 2024). "Using a zebrafish melanoma model, we show that MITF decreases ROS-mediated DNA damage in vivo." (PMID 39277608, 2024). "This is because microphthalmia-associated transcription factor (MITF), a member of the MiT/TFE family of transcription factors that includes TFE3, serves as a master regulator of melanocyte biology and acts as a lineage survival oncogene in melanoma." (PMID 39727945, 2024). "In addition, S100 protein family, Microphthalmia-associated transcription factor (MITF), SOX10, etc. have been proven to be diagnostic molecular markers for melanoma." (PMID 37427124, 2023). "Interestingly, enhancer E_763, potentially targeting the classic melanoma driver gene MITF, was supported by our HiChIP data." (PMID 37904237, 2023).
melanoma (continued). "In addition, MITF upregulates HIF-1α to enhance melanoma cell survival by directly binding to the HIF-1α promoter." (PMID 36901857, 2023). "To evaluate the effects of HLCE on melanogenesis at the molecular level, we measured the expression of key melanogenic genes, including Microphthalmia-associated transcription factor (MITF) and TYR in B16F1 melanoma cells using quantitative reverse transcription (qRT)-PCR." (PMID 38068559, 2023). "Mostly, this analysis categorized melanoma tumors into two distinct transcriptional cell states, such that tumors characterized by high levels of the MITF transcription factor were found to also contain cells with low MITF and elevated levels of the AXL kinase." (PMID 36675114, 2023). "Moreover, oncogenic MITF amplifications are found in melanomas, and overactivity of MITF drives melanoma formation." (PMID 36834926, 2023). "The glycolysis pathway controls the expression of MITF to assist melanoma cell cycle progression." (PMID 36675114, 2023). "Of note, MITF, the master regulator of melanoma, is among TFs recognizing such motifs." (PMID 37400441, 2023). "GREB1 Is4 was highly expressed with MITF in both benign nevi and melanoma samples." (PMID 37658191, 2023). "They observed that differences in the levels of MITF and Interferon-gamma (IFN-γ) led to innate resistant melanoma cell subpopulations MITF (Extremelyhi) and MITF (low) cell subsets have two types of melanoma cells that present different characteristics and responses to therapy." (PMID 37174106, 2023). "The promoter of the MITF gene, located directly upstream of the melanocyte isoform, is regulated by various transcription factors and signaling pathways that are involved in melanocyte and melanoma biology." (PMID 37893942, 2023). "Furthermore, a strategy for melanoma cells to gain a high proliferation rate is to avoid high MITF expression levels." (PMID 37123908, 2023). "Moreover, we found significant correlations between ICOS mRNA with AXL and MITF mRNA expression in the melanoma cell lines from the GDSC (ICOS/AXL: ρ = -0.457, P = 0.008; ICOS/MITF: ρ = 0.441, P = 0.010; N = 33)." (PMID 37259155, 2023). "Besides CDKN2A, other genes potentially associated with familial melanoma have also been investigated in Brazilian melanoma-prone families, such as CDK4, MITF, and TERT promoter variants." (PMID 37958811, 2023). "Moreover, it has been shown that during BRAF inhibitor treatment melanoma cells can lose MITF expression and de‐differentiate, marking the transition to an invasive subpopulation of treatment‐resistant cells." (PMID 36251678, 2023). "This might have a substantial effect on the levels of MITF in melanocytes and melanoma cells, as cAMP signaling increases MITF gene expression, whereas ERK activity promotes MITF protein degradation." (PMID 37762683, 2023). "In summary, our results highlight a mechanism by which post-translational modification of MITF regulates its ability to bind its targets and thereby control its ability to coordinate the gene expression programs that underpin melanocyte and melanoma proliferation and differentiation." (PMID 37770430, 2023). "In particular, this review has described the impact of BRAF mutational status on melanogenesis through a mechanism strictly related to MITF, since MITF-mediated increase in melanogenesis enzymes and melanosomal markers represent key players in melanoma progression." (PMID 37627054, 2023). "Next, we explored whether changes in the MITF level and activity during alternating periods of trametinib withdrawal and rechallenge were accompanied by changes in other melanoma cell subpopulations." (PMID 37175614, 2023).